GUK1 (guanylate kinase 1)
Description:
Catalyzes the phosphorylation of GMP to GDP. Essential enzyme for recycling GMP and indirectly, cyclic GMP (cGMP). Involved in the cGMP metabolism in photoreceptors (By similarity). It may also have a role in the survival and growth progression of some tumors. In addition to its physiological role, GUK1 is essential for converting prodrugs used for the treatment of cancers and viral infections into their pharmacologically active metabolites, most notably acyclovir, ganciclovir, and 6-thioguanine and its closely related analog 6-mercaptopurine.
Synonyms: GMK; MTDPS21
Tractability: Small molecule: a structure with a bound ligand is known. Antibody: the Human Protein Atlas places it where antibodies can reach. PROTAC: ubiquitination databases record sites on it; its protein half-life has been measured.
Target class: Enzyme; Transferase
Gene: Protein-coding gene on chromosome 1 (228,139,962 to 228,148,984, forward strand). Ensembl gene ENSG00000143774.
Subcellular location: Photoreceptor inner segment; Cytoplasm, cytosol; Mitochondrion (Isoform 2)
Subcellular location (Human Protein Atlas): Plasma membrane; Golgi apparatus
Pathways (Reactome):
Drug ADME: Azathioprine ADME
Metabolism: Interconversion of nucleotide di- and triphosphates
Gene Ontology:
Molecular function: GMP kinase activity; protein binding; ATP binding
Biological process: dGDP biosynthetic process; purine nucleotide metabolic process; xenobiotic metabolic process; nucleobase-containing small molecule interconversion; dATP metabolic process; dGMP metabolic process; GDP biosynthetic process; GDP-mannose metabolic process; glycoprotein transport; GMP metabolic process
Cellular component: mitochondrion; cytosol; photoreceptor inner segment
Genetic constraint (gnomAD): Loss-of-function variants: 15 observed, 20.65 expected, observed/expected ratio (o/e) 0.73, 90% interval 0.49 to 1.12. The upper end of that interval is the gene's LOEUF score, 1.12, which puts it in group 4 of 6, group 1 being the genes least tolerant of losing a copy. Missense variants: 235 observed, 254.31 expected, observed/expected ratio (o/e) 0.92, 90% interval 0.83 to 1.03. Synonymous variants: 95 observed, 108.62 expected, observed/expected ratio (o/e) 0.87, 90% interval 0.74 to 1.04.
Homologues: Orthologues: macaque GUK1 (96% identical), dog GUK1 (90% identical), guinea pig GUK1 (85% identical), rat Guk1 (81% identical), mouse Guk1 (79% identical), zebrafish guk1a (67% identical), tropical clawed frog guk1 (63% identical), zebrafish guk1b (63% identical), chimpanzee GUK1 (56% identical), Drosophila melanogaster CG11811 (53% identical), Caenorhabditis elegans guk-1 (50% identical).
Diseases named in the same sentence as GUK1 in open-access papers:
GUK1 is named in the same sentence as 10 diseases in open-access papers, as found by Europe PMC text mining. Sharing a sentence is not in itself a finding about the gene and the disease. The quoted sentences say what the papers report.
lung carcinoma (1 paper, 2020). "GUK1 is a target for a number of cancer chemotherapeutic agents; however among the 528 TCGA samples, while deletions of GUK1 was lethal in 93% of the normal controls, it was not lethal in 71% of the lung cancers." (PMID 32085724, 2020).
Sepsis (1 paper, 2024). Sepsis is defined as life-threatening organ dysfunction caused by a dysregulated host response to infection. "Mitochondria-related genes (FIS1, FKBP8, GLRX5, GUK1) were underexpressed in the sepsis group, negatively correlated with survival, and mainly distributed in immune cells." (PMID 38755528, 2024). "We compared the gene expression levels of both groups and found that FIS1, FKBP8, GLRX5, and GUK1 were underexpressed in the sepsis group but overexpressed in the SIRS group." (PMID 38755528, 2024). "Survival analysis showed that low expression of GUK1 in patients with sepsis could prolong their survival time." (PMID 38755528, 2024). "Therefore, we speculate that low expression of GUK1 is beneficial for the survival of patients with sepsis, and follow-up studies can use this as a starting point." (PMID 38755528, 2024). "In this study, we identified for the first time that four mitochondrial genes (FIS1, FKBP8, GUK1, GLRX5) can significantly impact the prognosis of sepsis patients, with high sensitivity and specificity for sepsis." (PMID 38755528, 2024).
cancer (6 papers, 2017 to 2025). A tumor composed of atypical neoplastic, often pleomorphic cells that invade other tissues. "For example, the protein encoded by GUK1 is thought to be a good target for cancer chemotherapy." (PMID 34863158, 2021). "For malignant cells, consistently upregulated metabolic genes were predominantly associated with cancer hallmark pathways, including glycolysis (GAPDH, GPI and LDHA), OXPHOS (COX6B1 and ATP5MC2), and nucleotide metabolism (TK1, GUK1, NME1)." (PMID 39393173, 2024).
tumor (4 papers, 2019 to 2026). "Specifically, GUK1 is an enzyme responsible for recycling GMP and has been indicated to play a role in tumor growth and survival." (PMID 38427613, 2024). "Statistical results showed that the correlations between two candidate tumor gene biomarkers (ATP6V0B and GUK1) were extremely strong, with correlations greater than 0.8." (PMID 34863158, 2021).
GUK1 also shares sentences with these, for which no sentence is quoted: infection (2 papers); breast tumors (1); glioma (1); liver fibrosis (1); malaria (1); psychiatric disorder (1).